LSM14B (LSM family member 14B)
Description:
mRNA-binding protein essential for female fertility, oocyte meiotic maturation and the assembly of MARDO (mitochondria-associated ribonucleoprotein domain), a membraneless compartment that stores maternal mRNAs in oocytes. Ensures the proper accumulation and clearance of mRNAs essential for oocyte meiotic maturation and the normal progression from Meiosis I to Meiosis II in oocytes. Promotes the translation of some oogenesis-related mRNAs. Regulates the expression and/or localization of some key P-body proteins in oocytes. Essential for the assembly of the primordial follicle in the ovary.
Synonyms: C20orf40; FAM61B; RAP55B; FT005; bA11M20.3; FLJ25473; LSM13
Tractability: PROTAC: UniProt records ubiquitination sites on it; ubiquitination databases record sites on it; its protein half-life has been measured.
Gene: Protein-coding gene on chromosome 20 (62,122,444 to 62,136,728, forward strand). Ensembl gene ENSG00000149657.
Subcellular location: Cytoplasm, Cytoplasmic ribonucleoprotein granule
Subcellular location (Human Protein Atlas): Vesicles
Gene Ontology:
Molecular function: protein binding; RNA binding
Biological process: maternal mRNA clearance; meiotic cell cycle process involved in oocyte maturation; membraneless organelle assembly; oogenesis; ovarian follicle development
Cellular component: cytoplasmic ribonucleoprotein granule
Genetic constraint (gnomAD): Loss-of-function variants: 8 observed, 38.36 expected, observed/expected ratio (o/e) 0.21, 90% interval 0.12 to 0.38. The upper end of that interval is the gene's LOEUF score, 0.38, which puts it in group 1 of 6, group 1 being the genes least tolerant of losing a copy. Missense variants: 396 observed, 497.44 expected, observed/expected ratio (o/e) 0.8, 90% interval 0.73 to 0.87. Synonymous variants: 219 observed, 204.87 expected, observed/expected ratio (o/e) 1.07, 90% interval 0.96 to 1.2.
Homologues: Orthologues: chimpanzee LSM14B (100% identical), macaque LSM14B (99% identical), mouse Lsm14b (95% identical), rat Lsm14b (94% identical), pig LSM14B (92% identical), dog LSM14B (83% identical), guinea pig LSM14B (83% identical), tropical clawed frog lsm14b (75% identical), rabbit LSM14B (61% identical), zebrafish lsm14b (56% identical), Drosophila melanogaster tral (43% identical), Caenorhabditis elegans car-1 (36% identical). Paralogues in human: LSM14A (57% identical).
Diseases named in the same sentence as LSM14B in open-access papers:
LSM14B is named in the same sentence as 8 diseases in open-access papers, as found by Europe PMC text mining. Sharing a sentence is not in itself a finding about the gene and the disease. The quoted sentences say what the papers report.
female infertility (2 papers, 2022 to 2023). Diminished or absent ability of a female to achieve conception. "Given that oocyte quality is a key limiting factor in female fertility, the female infertility in Lsm14b KO female mice could be attributed to decline in oocyte quality." (PMID 37578641, 2023).
Infertility (1 paper, 2023). "Thus, infertility in Lsm14b‐KO females was caused, at least in part, by failure of oocytes to progress to metaphase II." (PMID 37083226, 2023). "Deletion of Lsm14b results in female‐specific infertility and a phenotype characterized by oocytes incompetent to complete meiosis and early embryogenesis." (PMID 37083226, 2023).
multiple sclerosis (1 paper, 2021). A progressive autoimmune disorder affecting the central nervous system resulting in demyelination. "LSM14B showed a relationship with the BP of “Inhibition of oligodendrocyte precursor cell differentiation by Wnt signaling in multiple sclerosis”, a pathway involved in chronic demyelinating diseases." (PMID 34638387, 2021).
cancer (2 papers, 2021 to 2023). A tumor composed of atypical neoplastic, often pleomorphic cells that invade other tissues. "We investigated mutations of LSM genes in BRCA patients from TCGA Pan-Cancer Atlas (n = 1082 patients) in the cBioPortal platform, and found surprisingly high rates of alterations in LSM1 (25%), LSM2 (11%) LSM4 (8%), and LSM14B (23%)." (PMID 34638387, 2021). "Similarly, some progressors (CHMP4B, CSTF1, and LSM14B) and suppressors RBPs (ATP5F1A, GTF2E2, RTF1, ELAC2, LRRC47, and MRM3) have never been associated with COAD or READ, but present oncogenic properties in other cancer types." (PMID 37384253, 2023). "Meanwhile, we found that LSM7 and LSM14B proteins were not significantly differentially expressed between normal and cancer tissues." (PMID 34638387, 2021).
tumor (2 papers, 2021 to 2022). "LSM12, LSM14A, and LSM14B overexpression is also associated with higher tumor-related immune checkpoints (e.g., PD-L1, B7-H3, and PVR) expression and increased therapeutic insensitivity to immune checkpoint blockade (ICB)." (PMID 35646684, 2022). "The LSM family has 13 members (LSM1~LSM14B) which were strongly associated with tumorigenesis and metastasis of several tumor types." (PMID 34638387, 2021). "To further investigate the underlying role of LSM12, LSM14A, and LSM14B in tumor cell proliferation and invasion, we transfected SNU-387 cells with si-LSM12, si-LSM14A, and si-LSM14B RNAs." (PMID 35646684, 2022). "We also found that tumors with higher expression of LSM12, LSM14A, and LSM14B had higher expression of tumor-related immune checkpoints (e.g., PD-L1, B7-H3, and PVR), which are important for the immunosuppressive phenotype in malignancies." (PMID 35646684, 2022). "Taken together, these findings suggest the critical pro-tumor effects of LSM12, LSM14A, and LSM14B overexpression on HCC tumor cell proliferation and metastasis." (PMID 35646684, 2022). "Of note, we identified the potential inhibition effects of LSM12, LSM14A, and LSM14B on tumor immunity, which laid a novel foundation to further explore the role of LSM family members as novel potential therapeutic targets in HCC." (PMID 35646684, 2022). "In this report, we observed evidence of LSM14B overexpression that affected outcomes of the survival analysis and increasing expression levels in more progressive tumor stages." (PMID 34638387, 2021). "Additionally, we preliminarily demonstrated knockdown of LSM12, LSM14A, and LSM14B significantly inhibited tumor cell proliferation and invasion." (PMID 35646684, 2022). "Interestingly, LSM12, LSM14A, and LSM14B were observed to play critical roles in the T-cell receptor signaling pathway, suggesting their potential effects on tumor immunity in HCC." (PMID 35646684, 2022). "Of note, higher expression of tumor-related immune checkpoints (e.g., PD-L1, B7-H3, and PVR) was also observed in tumors with LSM12, LSM14A, and LSM14B overexpression." (PMID 35646684, 2022). "The CCK-8 assay demonstrated that tumor cell proliferation was notably inhibited in LSM12, LSM14A, and LSM14B depleted SNU-387 cells (P <0.0001)." (PMID 35646684, 2022).
LSM14B also shares sentences with these, for which no sentence is quoted: asthma (1 paper); breast carcinoma (1); breast tumors (1).